CYP3A4 (cytochrome P450 family 3 subfamily A member 4)
Diseases named in the same sentence as CYP3A4 in open-access papers (continued):
Sharing a sentence is not in itself a finding about the gene and the disease.
heart diseases (4 papers, 2012 to 2024). "In this study, participants with CYP3A4*1G genetic mutation had a 1-fold to 2-fold increase in the incidence of cardiac diseases than participants without genetic mutation." (PMID 38117809, 2023). "The top one CYP3A4 for example is shared by 41 drugs, out of 181 total heart disease related drugs." (PMID 22401035, 2012).
psychiatric disorder (3 papers, 2014 to 2024). A disorder characterized by behavioral and/or psychological abnormalities, often accompanied by physical symptoms. "In addition, zopiclone was a commonly prescribed nonbenzodiazepine hypnotic drug and it was used as a short-term treatment strategy to improve sleep in a number of psychiatric disorders, where CYP3A4 was the major enzyme involved in zopiclone metabolism." (PMID 39840087, 2024).
gastrointestinal disorders (2 papers, 2017 to 2024). "in cytochrome P540 3A4 (CYP3A4), concomitant diseases, i.e. liver, renal or gastrointestinal disorders, or co-administered drugs, i.e. CYP3A4 inhibitors and inducers." (PMID 29190894, 2017).
hematologic malignancies (2 papers, 2021 to 2025). "A large number of treatments administered in hematologic malignancy patients, including chemotherapy agents, are metabolized through the cytochrome P-450 (CYP) pathway, with potential important interactions with agents, such as voriconazole and posaconazole, both strong inhibitors of CYP3A4." (PMID 34432216, 2021).
gastrointestinal disease (1 paper, 2025). A disease that occurs in the gastrointestinal system, excluding the hepatobiliary system. "Clinical conditions or interventions that disrupt the microbiota—such as broad-spectrum antibiotic therapy, gastrointestinal disease, or major dietary changes—have been associated with altered pharmacokinetics of CYP3A4 substrates." (PMID 41011221, 2025).
infectious disease (1 paper, 2021). A disorder directly resulting from the presence and activity of a microbial, viral, or parasitic agent in humans. "CYP3A4 is a major metabolizing enzyme for most drugs used in tropical infectious diseases, including PZQ." (PMID 34531744, 2021).
inflammation (1 paper, 2025). Aberrant reaction of the microcirculation characterized by movement of fluid and leukocytes from the blood into extravascular tissues. "The observed induction of CYP3A4 by sitagliptin could be attributed to sitagliptin’s anti-inflammatory and hepatoprotective effects, thereby inhibiting the cytokine-induced suppression of CYP3A4 that is often observed in hepatic inflammation and preneoplasia." (PMID 40786041, 2025).
metabolic disorders (1 paper, 2022). "Impaired drug metabolism, metabolic disorders, and competition for CYP3A4 with other drugs (e.g., statins) are possible mechanisms leading to a lower concentration of clopidogrel’s active metabolite and insufficient antiplatelet effects." (PMID 35562942, 2022).
musculoskeletal disorders (1 paper, 2021). "On the other hand, the prevalence of oral analgesic use, in CYP3A4 (42.8%) and NO-CYP3A4 (42.1%), was similar to that previously reported in individuals with musculoskeletal disorders with lipid-lowering drug use (41.0%)." (PMID 34698118, 2021).
CYP3A4 also shares sentences with these, for which no sentence is quoted: respiratory depression (7 papers); end-stage renal disease (6); Arthritis (4); hepatitis C (4); renal carcinoma (4); Anorexia (3); chronic hepatitis C (3); hyperlipidemia (3); inflammatory bowel disease (3); Insulin resistance (3); renal cell carcinoma (3); -immune diseases (2); acute coronary syndrome (2); acute leukemia (2); acute myocardial infarction (2); chronic gout (2); cognitive deficits (2); Colon (2); dyspepsia (2); electrolyte disturbances (2); End Stage Liver Disease (2); G6PD deficiency (2); glioma (2); hemorrhage (2); Hypoalbuminemia (2); Hypoglycemia (2); Hyponatremia (2); interstitial pulmonary fibrosis (2); kidney (2); lymphoma (2).
A further 127 diseases each share a sentence with CYP3A4 in 2 papers or fewer.